CD300A (CD300a molecule)
Diseases named in the same sentence as CD300A in open-access papers (continued):
Sharing a sentence is not in itself a finding about the gene and the disease.
tumor (continued). "While most studies emphasize its immune cell–mediated effects, emerging evidence suggests that CD300a may directly influence tumor progression by regulating immune homeostasis, intracellular signaling, and tumor microenvironment interactions." (PMID 40507267, 2025). "Importantly, this effect was independent of co-treatment with other immune checkpoint inhibitors, such as PD-1 blockade, confirming the intrinsic anti-tumor capability of CD300a inhibition." (PMID 40507267, 2025). "In addition, the ligands of CD300a, PS and PE, are known to be present on the surface of tumor cells in gastric, ovarian, and melanoma cancers." (PMID 40507267, 2025). "Taken together, these results suggested that CD300A might augment tumor immunity via suppression of tumor-infiltrating Treg cells also in humans." (PMID 34751648, 2021). "Importantly, blocking the interaction of CD300a with phosphatidylserine was shown to enhance the killing of RKO or 293T tumor cells by bulk human NK cell cultures." (PMID 34503073, 2021). "On the other hand, the balance of TLR3 and CD300a expressions in DCs may also be important for Treg activation and tumor development." (PMID 34751648, 2021). "Four hours after incubation in the presence of the culture supernatant, Cd300a−/− BMDCs expressed higher levels of Ifnb than did wild-type BMDCs, suggesting that CD300a suppressed the Ifnb expression induced by a tumor-derived immune mediator in the culture supernatant." (PMID 34751648, 2021). "Further analysis of human CD300A expressions on T cells in tumor microenvironment is needed." (PMID 34751648, 2021). "We focus here on the critical immune checkpoint PD-1 and on Siglec-7/p75/AIRM1/CD328, LAIR-1/p40/CD305, and IRp60/CD300a, originally identified in our labs, representing additional immune checkpoints possibly dampening anti-tumor NK cell responses in given pathological settings." (PMID 33013909, 2020). "However, does CD300A have other mechanisms or target proteins in the regulation of tumor cell function?" (PMID 29938007, 2018). "In briefly, CD300A may contribute to tumor proliferation and apoptosis by upregulating PECAM1 and ADCY7, in addition to recruiting PTP in AML cells." (PMID 29938007, 2018). "It was shown that CD300a could bind to phosphatidylserine, which was expressed on both tumor cells and apoptotic cells, resulting in decreased cytotoxicity of NK cells." (PMID 30333226, 2018). "Furthermore, western blot analysis of tumor tissues isolated from the mice indicated decreasing levels of p-AKT in tissues with CD300A knockdown." (PMID 26435477, 2015). "Moreover, CD300A was capable of binding to tumor cells through interaction with phosphatidylserine (PS) in tumor cells, and blocking CD300A-PS interaction resulted in enhanced NK cell killing of tumor cell." (PMID 26435477, 2015). "Besides genes with metabolic functions, these include cell type-selective genes associated with immune regulation and tumor progression, e.g., LRP5, CD300A, MAP3K8 and ANGPTL4." (PMID 25968567, 2015). "Importantly, we found that the levels of CD300A in DLBCL tumor tissues were significant greater than that in lymphoid tissues from benign diseases, suggesting a potential clinical significance of CD300A for DLBCL." (PMID 26435477, 2015). "However, since CD300a is abundantly expressed in various immune cells, it is challenging to define the contribution of CD300a as a tumor progression mediator, making it difficult to conclusively define the therapeutic benefit of CD300a blockade in cancer immunotherapy." (PMID 40507267, 2025). "Therefore, CD300a-mediated inhibition of TH1 activity may contribute to immune evasion by suppressing anti-tumor responses." (PMID 40507267, 2025).
tumor (continued). "Although CD300a expression is primarily restricted to hematopoietic cells such as monocytes, macrophages, and dendritic cells, as confirmed by databases including the Human Protein Atlas, several studies have investigated its potential roles within the tumor immune microenvironment of solid tumors." (PMID 40507267, 2025). "In particular, it remains unclear whether CD300a exerts its tumor-promoting effects through direct action on malignant cells or indirectly by modulating immune cells such as monocytes and dendritic cells within the tumor microenvironment." (PMID 40507267, 2025). "However, it is interesting to note that CD300A inhibits the apoptosis through PECAM1 but not ADCY7 in U937 cells, implying the unknown mechanisms by which CD300A promotes tumor progression." (PMID 29938007, 2018). "Tumor-derived extracellular vesicles carrying PS bind to CD300a on DCs, and suppress TLR3-mediated IFN-β production, leading to enhanced in vitro accumulation of tumor-infiltrating Tregs." (PMID 40507267, 2025). "In the tumor microenvironment (TME), PS-positive tumor EVs contribute to inhibition of TLR3-mediated IRF3 and IFN-β expression through binding with CD300a on DCs." (PMID 40507267, 2025). "For example, CD300a-mediated inhibition of DC type I IFN production is critical for T cell priming, but the nature of the tumor as well as cues from the microenvironment play a role." (PMID 40507267, 2025). "Tumor growth curves of WT (PBS, n = 6; GW4869, n = 9) (D) or Cd300afl/fl (n = 4 each) (E) and Cd300a−/− mice (PBS, n = 7; GW4869, n = 9) (D) or Cd300afl/fl;Itgax-Cre (n = 6 each) (E) that were treated with GW4869 or PBS three times (days 14, 18, and 21)." (PMID 34751648, 2021). "Here, we investigated the role of CD300a in tumor development and demonstrate that CD300a inhibits TEV-mediated interferon-β (IFN-β) production by DCs and suppresses the activation of tumor-infiltrating Treg cells and tumor development." (PMID 34751648, 2021). "Taken together, these data suggest that CD300a inhibits the TLR3–TRIF signaling pathway for IFN-β production at the endosomes in DCs, resulting in the suppression of Treg cell activation and tumor development." (PMID 34751648, 2021). "Both PECAM1 and ADCY7 promote tumor progression through the AKT pathway, showing the same molecular mechanism as CD300A." (PMID 29938007, 2018). "Both PECAM1 and ADCY7 promoted tumor progression through the AKT pathway, showing the same molecular mechanism as CD300A." (PMID 29938007, 2018). "The results of this study showed that CD300A knockdown inhibited proliferation and migration and promoted apoptosis in AML cell line U937, suggesting CD300A functions as a tumor promoter in AML." (PMID 29938007, 2018). "We demonstrated that CD300A regulates the proliferation and apoptosis of AML cells as a tumor promoter, playing a positive role in AML as a potential therapeutic target." (PMID 29938007, 2018). "Decreasing CD300A expression in DLBCL cells significantly inhibited cell proliferation in vitro and suppressed tumor growth in a xenograft mouse model in vivo." (PMID 26435477, 2015). "Conversely, CD300a/c− CD4+ T cells are more related to a TH17 profile, expressing IL-17A, which may promote tumor progression in certain tumor microenvironments." (PMID 40507267, 2025). "Here, partial co-localization of CD300a and MCT was observed in ductal epithelial cells, suggesting potential phenotypic modulation or interaction between MC-derived mediators and epithelial components in the tumor microenvironment." (PMID 41155492, 2025). "The Treg cell population was larger in the tumor, but not the draining lymph nodes, of Cd300a−/− mice compared with that of wild-type mice." (PMID 34751648, 2021). "Therefore, decreased expression of CD300A and SIGLEC7 can facilitate the tumor cytotoxicity of CIK cells." (PMID 30333226, 2018). "Therefore, we predicted that CD300A modulates the AKT pathway and thereby affects tumor progression." (PMID 29938007, 2018).
tumor (continued). "For instance, tumor cell antigen modulation allows the cells to escape from recognition by T cells and NK cells, thereby downregulating T cell- and NK cell-related immune factors (IL18 and CD300A)." (PMID 28355233, 2017). "Furthermore, using a xenograft animal model, we found that decreasing levels of CD300A in OCI-Ly01 and Farage cells significantly inhibited tumor formation in vivo." (PMID 26435477, 2015). "Moreover, studies on CD300a/c expression in human CD4+ memory T cell subsets have demonstrated that CD300a/c+ CD4+ T cells are largely TH1 and produce IFN-γ which is essential for anti-tumor immunity." (PMID 40507267, 2025). "While mast cells are not considered major effectors of anti-tumor immunity in most solid tumors, these observations suggest that CD300a may contribute to maintaining an immunosuppressive environment." (PMID 40507267, 2025). "The apparent co-expression of MCT and CD300a in the epithelium of PA might reflect either technical proximity to infiltrating MCs or a potential uptake of MCs-derived proteases such as MCT by tumor cells, rather than true endogenous expression." (PMID 41155492, 2025). "However, we also observed that CD300a was not expressed on tumor-infiltrating lymphocytes but was broadly expressed on myeloid cells, including populations of Ly6G+ neutrophils, CD11c+~high DCs, and CD11clowCD11b+ macrophages." (PMID 34751648, 2021). "According to these foundings, we predicted that CD300A affected the activation of AKT/mTOR signaling pathways by recruiting PTP, thereby regulating the expression of proliferation and apoptosis related genes and affecting the biological behavior of tumor cells." (PMID 29938007, 2018). "However, anti-CD300a mAb treatment did not result in a significant change in tumor weight." (PMID 40507267, 2025). "Given that cDC2 is involved in CD4+ T cell differentiation and activation, CD300a on cDC2, rather than cDC1, may regulate Treg cells activation by inhibiting the TLR3–IFN-β pathway in tumor microenvironment." (PMID 34751648, 2021).
infection (10 papers, 2016 to 2025). The state of being infected such as from the introduction of a foreign agent such as serum, vaccine, antigenic substance or organism. "Moreover, human B cells are susceptible to direct infection by dengue virus (DENV) via CD300a and support viral replication albeit low titers of infectious virions were released." (PMID 36012490, 2022). "We observed a reduced number of granulomatous areas, specifically at the later stages of infection in the liver of anti-CD300a blocked mice, which further suggested its importance in controlling diseases outcome." (PMID 35116028, 2021). "The frequency of CD300a+ CD11c+ dendritic cells was also found to be increased by 11-18 fold (D7, 11.2 fold, p=0.031; D14,18.5 fold, p=0.017; D21, 18.4 fold, p=0.011) after infections." (PMID 35116028, 2021). "We observed increased numbers of CCR7+ and CD62L+ CD4+ T cells in anti-CD300a antibodies treated mice, which was significant at the later stages of infection (D14 and D21)." (PMID 35116028, 2021). "To validate CD300a’s role in the survival of parasites during the early immune responses mounted by the host, we quantified the expression levels of CD300a in mice spleens at days 7 (D7), 14 (D14), and 21(D21) post-infection." (PMID 35116028, 2021). "We first did an in vitro experiment in which pan T cells (containing both CD4+ and CD8+ T cells), obtained from parasite-infected animals post 14 days of infection, were co-cultured with anti-CD300a antibodies treated and parasite infected BMDC." (PMID 35116028, 2021). "A significant decrease in infection of more than 50% was observed between direct infection and 10 ug concentration of CD300a blocking antibody (p < 0.05)." (PMID 33643283, 2020). "Several recognition mechanisms of apoptotic cells by phagocytes were described during the infection of several viruses, such as those that recognize CD300a, TIM and TAM receptors, observed in DENV infection." (PMID 27723844, 2016). "The activation of cells with soluble leishmanial antigens (SLA) also increased CD300a mRNA (Mφ,23.8 fold, p= 0.047; BMDCs, 13.7 fold, p=0.038) and protein (Mφ, 7 fold, p=0.024; BMDCs, 6.6 fold, p=0.005) expression levels that was measured 24h post-infection." (PMID 35116028, 2021). "The expression of CD300a both, at mRNA and protein levels were found significantly increased in macrophages (Mφ) and BMDCs infected with L. donovani at all the time points, i.e., 12h, 24h, 36h being maximum at 24h post-infection." (PMID 35116028, 2021). "In addition, the expression levels of MHC I and MHC II genes were also found significantly elevated with increasing duration of infection in anti-CD300a treated mice." (PMID 35116028, 2021). "We hypothesized that induced expression of CD300a on antigen-presenting cells may have a significant impact on effector properties of activated T cells during infection." (PMID 35116028, 2021). "We observed that when CD300a was blocked on CD19+ B cells, a significant decrease in infection was observed in a concentration-dependent manner suggesting CD300a can be an attachment/entry factor or receptor for DENV in B cells." (PMID 33643283, 2020). "have described that human and mouse CD300a bind the four DENV serotypes and enhance the infection through clathrin-mediated endocytosis." (PMID 33643283, 2020). "Although DENV infection is not fully inhibited, the blockade of CD300a on B cells decreases the infection in a concentration-dependent manner, which further confirms that CD300a acts as an attachment and entry receptor for DENV infection in B cells." (PMID 36423184, 2022). "Because CD300a has been shown to inhibit toll-like receptor (TLR)-dependent inflammatory pathways, ligation of CD300a by DENV could inhibit or delay innate immune response against infection." (PMID 27584579, 2016).
cancer (6 papers, 2016 to 2025). A tumor composed of atypical neoplastic, often pleomorphic cells that invade other tissues. "This review highlights the immunoregulatory functions of CD300a and discusses its potential as a therapeutic target in cancer immunotherapy." (PMID 40507267, 2025). "Overall, these results demonstrated that the protein expression patterns of CD300A in most cancers agreed very well with the observed levels of mRNA." (PMID 35642341, 2023). "In the present study, we comprehensively assessed the prognostic implications of CD300s in 33 cancer types and we were able to confirm the adverse prognostic impact of CD300A in AML." (PMID 35642341, 2023). "Thus, delineating the temporal and spatial dynamics of CD300a expression across immune compartments is essential for developing effective cancer immunotherapies targeting this pathway." (PMID 40507267, 2025). "Collectively, these findings establish CD300a as a pleiotropic immunoregulatory molecule in both hematologic and non-hematologic malignancies, underscoring the need to further explore its broader relevance and therapeutic potential in cancer immunology." (PMID 40507267, 2025). "The integration of multimarker panels (MCT, CD163, CD300a, CK18) could improve diagnostic accuracy by distinguishing between benign proliferations with active stroma and low-differentiation carcinomas." (PMID 41155492, 2025). "Interestingly, CD300A, which is upregulated in most cancers, demonstrated an overall hypermethylation pattern." (PMID 35642341, 2023).
epithelial neoplasm (1 paper, 2025). A benign or malignant neoplasm that arises from and is composed of epithelial cells. "Furthermore, the role of CD300a in epithelial cells remains elusive: although classically known to inhibit activation signals in MCs and other myeloid lineages, its intracellular signaling pathways in epithelial neoplasms have yet to be elucidated." (PMID 41155492, 2025).
CD300A also shares sentences with these, for which no sentence is quoted: glioblastoma (2 papers); Hematologic Malignancies (2); autoimmune disease (1); Crohn disease (1); diabetic nephropathy (1); focal segmental glomerulosclerosis (1); food allergy (1); head and neck squamous cell carcinoma (1); lymphoma (1); ovarian carcinoma (1); pancreatic adenocarcinoma (1); peritonitis (1); Respiratory Disease (1); sarcoidosis (1); squamous cell carcinoma (1); ulcerative colitis (1); uterine corpus endometrial carcinoma (1).